CNTN2 (contactin 2)
Diseases named in the same sentence as CNTN2 in open-access papers:
CNTN2 is named in the same sentence as 79 diseases in open-access papers, as found by Europe PMC text mining. Sharing a sentence is not in itself a finding about the gene and the disease. The quoted sentences say what the papers report.
epilepsy (7 papers, 2014 to 2023). A brain disorder characterized by episodes of abnormally increased neuronal discharge resulting in transient episodes of sensory or motor neurological dysfunction, or psychic dysfunction. "To date, 13 mutations in the CNTN2 have been associated with epilepsy and FAME5, including 7 missense mutations, splice variants, and 2 small deletions." (PMID 37359369, 2023). "A deleterious homozygous variant in the CNTN2 gene was previously reported to cause autosomal recessive cortical myoclonic tremor and epilepsy." (PMID 34691156, 2021). "Here, we reported one new case, who presented with epilepsy, carrying a novel homozygous frameshift variant in CNTN2." (PMID 34691156, 2021). "Mutations in CNTN2 and CNTNAP2 (the genes encoding contactin-2 and Caspr2, respectively) have been identified in autism spectrum disorder, epilepsy, Tourette’s syndrome, schizophrenia and ADHD." (PMID 24913350, 2014). "Pathogenic variants in CNTN2 and ST3GAL5 are associated with myoclonic epilepsy and epilepsy, respectively." (PMID 34816733, 2021). "A homozygous single base pair deletion (c.503_503delG) of contactin-2 was identified to be present in individuals affected with autosomal recessive cortical myoclonic tremor and epilepsy in a consanguineous Egyptian family." (PMID 29249937, 2017). "Since then, there has been no further report confirming the association of CNTN2 and epilepsy." (PMID 34691156, 2021). "Moreover, its paralogs CNTN2 and CNTN4 are associated with epilepsy and autism, respectively." (PMID 30148849, 2018). "Several observations indicate that contactin-2 may play a role in the onset of epilepsy." (PMID 29249937, 2017).
glioma (7 papers, 2016 to 2026). A benign or malignant brain and spinal cord tumor that arises from glial cells (astrocytes, oligodendrocytes, ependymal cells). "Recently, CNTN2 was reported to involve in the development of some cancers, such as hepatocellular carcinoma, glioma, and lung adenocarcinoma." (PMID 37105033, 2023). "Yan et al27 revealed the protein level of CNTN2 was higher in high‐grade glioma cells and tissues and lower in low‐grade glioma cells and tissues." (PMID 30353687, 2018). "CNTN2 has been shown to promote glioma stem-like cell proliferation through regulation of EGFR-, HES1-, and APP/AICD-associated signaling pathways, and its knockdown suppresses tumor cell growth in vitro, supporting a functional role in glioblastoma progression." (PMID 41596752, 2026). "CNTN2, a cell adhesion protein, is a downstream protein of RACK1, which affects the growth and differentiation of glioma cells through the RTK/Ras/MAPK signaling pathway." (PMID 32328342, 2020). "Beyond their association with survival, experimental and transcriptomic studies provide evidence that CNTN2 and TSPAN2 may play active roles in glioma biology." (PMID 41596752, 2026).
schizophrenia (7 papers, 2014 to 2024). A major psychotic disorder characterized by abnormalities in the perception or expression of reality. "Multiple pieces of evidence have linked CNTN2, CNTNAP2, GABBR2, and NTRK3 to neuropsychiatric disorders, including schizophrenia." (PMID 30323833, 2018). "CNTN2 has previously been associated with WHR and schizophrenia." (PMID 33182605, 2020). "In the network, candidate genes with nominal significance such as ANKS1B, CNTN2, CNTNAP2, GABBR2, NCOR2, and NTRK3 also may be involved in the pathology of schizophrenia." (PMID 30323833, 2018). "Elevated expression of CNTN2 and EFHD1 was specifically found in disorganized schizophrenia." (PMID 28809853, 2017).
Alzheimer disease (4 papers, 2014 to 2020). A progressive, neurodegenerative disease characterized by loss of function and death of nerve cells in several areas of the brain leading to loss of cognitive function such as memory and language. "Contactin-2 has been implicated in neurodegenerative diseases, such as Alzheimer’s disease (AD), multiple sclerosis, and loss of cognitive abilities in contactin-2 knockout mice." (PMID 33100957, 2020). "However, decreased levels of CNTN2 in cerebrospinal fluid observed in Alzheimer’s disease patients suggests a relationship between circulating CNTN2 and brain pathology." (PMID 31623079, 2019). "Finally, contactin-2 levels were decreased in Alzheimer’s disease brain samples correlating inversely with elevated BACE1 levels in the same samples." (PMID 24405708, 2014).
breast carcinoma (4 papers, 2011 to 2022).
Cognitive impairment (4 papers, 2010 to 2023). Abnormal cognition is characterized by deficits in thinking, reasoning, or remembering. "We identified and positively validated five novel proteins (NCAM2, NPTXR, NRXN2, RELN, and CNTN2) as promising biomarkers for cognitive impairment following aSAH." (PMID 35602555, 2022). "Murine knockout of Tag1 (murine CNTN2 ortholog) found evidence of cognitive impairments based on the Morris water maze and novel object recognition tests, as well as reduced spontaneous motor activity, abnormal gait coordination and increased response latency to noxious stimulation." (PMID 37422595, 2023).
Autoimmunity (3 papers, 2009 to 2021). The occurrence of an immune reaction against the organism's own cells or tissues. "The contactin-2/TAG-1-directed autoimmunity induces encephalitis characterized by a preferential inflammation of the gray matter of the spinal cord and cortex." (PMID 21358979, 2010).
encephalitis (3 papers, 2010 to 2024). An acute inflammatory process affecting the brain parenchyma. "Seizures associated with CASPR2 encephalitis may result from disrupted interaction between CASPR2 and contactin-2, impairing Kv1 channel expression and leading to hyperexcitability and network dysfunction." (PMID 39539648, 2024).
malignant glioma (3 papers, 2006 to 2026). A grade III or grade IV glioma arising from the central nervous system. "In addition, CNTN2 has been reported to be co-amplified and overexpressed in subsets of malignant gliomas, suggesting that it may confer a selective growth advantage in specific molecular contexts." (PMID 41596752, 2026).
Obesity (3 papers, 2014 to 2019). Accumulation of substantial excess body fat. "It is noteworthy that contactin-2/TAG1 is a strong regulator of diet-induced obesity." (PMID 24659297, 2014). "This is the first study that examined the relationship between neurological markers CNTN2 and BDNF in circulating exosomes with biological predictors for poor neonatal iron endowment, including maternal anemia, obesity, and diabetes." (PMID 31623079, 2019).
sarcopenia (3 papers, 2022 to 2025). Progressive decline in muscle mass due to aging which results in decreased functional capacity of muscles. "They ultimately identified five candidate causal proteins associated with sarcopenia, including LILRB2, ASPN, CNTN2, ART4 and SOD2." (PMID 39949133, 2025). "We investigated the putatively potential causal effects of genetically predicted plasma protein levels on sarcopenia-related traits and identified three putatively causal proteins for ALM (LILRB2, ASPN, and CNTN2) and two for handgrip strength (ART4 and SOD2)." (PMID 35938019, 2022).
viral infection (3 papers, 2019 to 2025). "Our findings that human Contactin-2 Tag-1 antibody could be used to purify fetal CNSEs in a non-human primate model suggests that this methodology could be used to augment studies of perinatal viral infection in appropriate animal models." (PMID 40012720, 2021). "By contrast, POR, CNTN2, and HSD17B10 have not previously been associated with viral diseases." (PMID 41303479, 2025).
hepatocellular carcinoma (2 papers, 2015 to 2023). A malignant tumor that arises from hepatocytes. "It has been suggested that CNTN2 (also knows as contactin-2 or axonal glycoprotein TAG-1) is involved in the cell adhesion process and serves a critical function in the early stages of hepatocellular carcinoma." (PMID 25351872, 2015).
multiple sclerosis (2 papers, 2013 to 2020). A progressive autoimmune disorder affecting the central nervous system resulting in demyelination. "Cntn2 plays a role in the formation of axon connections and autoimmune responses to Cntn2 have been implicated in multiple sclerosis." (PMID 23874995, 2013).
oligodendroglioma (2 papers, 2012 to 2022). A well-differentiated (WHO grade II), diffusely infiltrating neuroglial tumor, typically located in the cerebral hemispheres. "CNTN2 was found to be highly expressed in oligodendrogliomas." (PMID 35053843, 2022).
T-cell lymphoma (2 papers, 2014 to 2023). "Moreover, missense mutations were detected in CD44 and CD19 (associated with acute myeloid leukemogenesis), LTK (associated with poorly differentiated adenocarcinoma), NOTCH2 (associated with diffuse large B-cell tumorigenesis), and CNTN2 (associated with T-cell lymphoma)." (PMID 36871023, 2023).
acute lymphoblastic leukemia (1 paper, 2024). Leukemia with an acute onset, characterized by the presence of lymphoblasts in the bone marrow and the peripheral blood. "CNTN2 was associated with acute lymphoblastic leukemia, B-cell lymphoma, malignant neoplasm of the thyroid gland, and malignant neoplasm of the ureter." (PMID 39003418, 2024).
amyloid (1 paper, 2018). "Interestingly, within the AD cases we observed a specific reduction in contactin-2 staining in areas resembling amyloid plaques (where probable plaques are shown by arrowheads)." (PMID 29859129, 2018). "Taken together, these data suggest that contactin-2 can influence the homeostasis of Aβ which may ultimately affect the formation of amyloid deposits and the pathogenesis of AD." (PMID 29859129, 2018).
anemia (1 paper, 2019). A reduction in the number of red blood cells, the amount of hemoglobin, and/or the volume of packed red blood cells. "Analysis of neonatal risk factors for brain ID (baby weight Z-score, maternal BMI, maternal anemia, and maternal diabetes) as predictors of exosomal CNTN2 and BDNF levels were performed." (PMID 31623079, 2019).
Anxiety (1 paper, 2022). Intense feelings of nervousness, tension, or panic often arise in response to interpersonal stresses. "For example, Contactin-2 (CNTN2) and Hepatocyte growth factor-like protein (MSP) were significantly correlated with anxiety and depression in the study of mouse proteomes by combining mass spectrometry." (PMID 35870967, 2022).
Arrhythmia (1 paper, 2022). Any cardiac rhythm other than the normal sinus rhythm. "Our data showed that restoration of Casq2 at a median (nonzero) distance of 53.8 μm from the nearest Cntn2-positive (Purkinje) cells was sufficient to prevent arrhythmias, indicating that distal (epicardial) cardiomyocytes, despite lacking Casq2, are not the cellular trigger for CPVT." (PMID 34990403, 2022).
CADASIL (1 paper, 2023). "There were four mutations identified in CNTN2, which has also been associated with familial adult myoclonic epilepsy (a known uncommon symptom of CADASIL and other CSVD), indicating a potential overlap in the phenotypic spectrum of the disease." (PMID 37422595, 2023).
cardiac conduction disease (1 paper, 2021). "Mice deficient in NCAM-1, but not CNTN2 or ALCAM, exhibited defects in PC gene expression and VCS patterning, as well as cardiac conduction disease." (PMID 34100064, 2021).
COVID-19 (1 paper, 2022). A disease caused by infection with severe acute respiratory syndrome coronavirus 2. "CNTN2 and TMCC2 occur in the same genomic region that is significantly associated with risk of poor COVID-19 outcomes in individuals with high European ancestry in Brazil." (PMID 36143338, 2022). "Our results included SNPs in the genes FBXO34, Contactin 2 (CNTN2), and Transmembrane And Coiled-Coil Domain Family 2 (TMCC2) which have been previously linked with COVID-19 severity." (PMID 36143338, 2022). "This included FBXO34, CNTN2, and TMCC2 previously linked with COVID-19 severity using association studies." (PMID 36143338, 2022).
dementia (1 paper, 2018). Loss of intellectual abilities interfering with an individual's social and occupational functions. "Contactin-2 was measured in CSF from two cohorts (selected from the Amsterdam Dementia Cohort), comprising samples from controls (cohort 1, n = 28; cohort 2, n = 20) and AD (cohort 1, n = 36; cohort 2, n = 70) using an analytically validated commercial enzyme-linked immunosorbent assay (ELISA)." (PMID 29859129, 2018).
depression (1 paper, 2022). "Gender subgroup analyses found that BST1 was correlated with neuroticism score in male CSF (r = − 0.011, P = 1.80 × 10− 5), while CNTN2 was correlated with depression score in female brain (r = − 0.013, P = 6.43 × 10− 4)." (PMID 35870967, 2022).
developmental delay (1 paper, 2022).
diabetes (1 paper, 2019). "There was a strong sex-specific relationship between maternal diabetes and exosomal CNTN2 (predictor-by-sex interaction p = 0.0005)." (PMID 31623079, 2019).
myeloid sarcoma (1 paper, 2023). A tumor mass composed of myeloblasts or immature myeloid cells.
neuromyotonia (1 paper, 2018). "This cohort study combined with a patient-led survey found that antibodies to the extracellular aspects of leucine-rich glioma inactivated protein, contactin-associated protein 2, and contactin 2 were variably present in 45% of patients with neuromyotonia." (PMID 30242309, 2018).
psoriasis (1 paper, 2017). An autoimmune condition characterized by red, well-delineated plaques with silvery scales that are usually on the extensor surfaces and scalp. "Notably, some genes strongly decreased in psoriasis lesions were elevated by IMQ in most strains (Syt8, Cdhr1, Cntn2)." (PMID 28279190, 2017).
tumor (25 papers, 2006 to 2026). "Proteins of interest identified by tandem MS-MS that were decreased in sera from tumor-bearing rats that were either OKN-007-treated or untreated included ABCA2, ATP5B, CNTN2, ITGA3, KMT2D, MYCBP2, NOTCH3, and VCAN." (PMID 35053843, 2022). "From this study, proteins of interest identified by tandem MS-MS that were decreased in sera from tumor-bearing rats treated with OKN-007, compared to untreated, included ABCA2, ATP5B, CNTN2, ITGA3, KMT2D, MYCBP2, NOTCH3, and VCAN." (PMID 35053843, 2022).
cancer (10 papers, 2012 to 2023). A tumor composed of atypical neoplastic, often pleomorphic cells that invade other tissues. "The hub genes identified by PPI network analysis include SYN1, CNTN2, FAIM2, MT3, and SH3GL2, which are involved in the pathogenesis of different cancers." (PMID 32328342, 2020). "Besides that, other CSV interactions also can be a predictive biomarker in other cancers, such as BRWD3 and PSMB8 in LUAD (P = 8E−04, log-rank test), as well as CNTN2 and HDAC11 (P = 0.01, log-rank test) in LUAD." (PMID 36180906, 2022).
neurological disorder (3 papers, 2015 to 2023). "By consulting relevant literature, 6 genes related to neurodevelopmental and neurological diseases (GPC5, CA10, DSCAM, IL1RAPL2, CNTN2, and SPOCK3) were verified by ELISA method." (PMID 37539343, 2023). "Finally, six genes/proteins related to neurodevelopmental and neurological diseases (GPC5, CA10, DSCAM, IL1RAPL2, CNTN2, and SPOCK3) were verified by ELISA." (PMID 37539343, 2023).
CNTN2 also shares sentences with these, for which no sentence is quoted: infection (16 papers); lymphoma (6); bladder cancer (3); HTLV-2 infection (3); leukemia (3); Astrocytoma (2); autism spectrum disorder (2); glioblastoma (2); neurodegenerative disease (2); T-cell leukemia (2); adenovirus infection (1); adult T-cell leukemia (1); autism (1); autoimmune disease (1); B-cell lymphoma (1); bladder tumors (1); chronic granulocytic leukemia (1); co-infection (1); Epileptic encephalopathy (1); esophageal squamous cell carcinoma (1); fibrosarcoma (1); fibrosis (1); HIV-1 infection (1); HTLV infection (1); Iron Deficiency (1); liver fibrosis (1); lung adenocarcinoma (1); lung carcinoma (1); male infertility (1); malignant neoplasm of the thyroid gland (1).
A further 15 diseases each share a sentence with CNTN2 in 1 paper.